NRP1 (neuropilin 1)
Diseases named in the same sentence as NRP1 in open-access papers (continued):
Sharing a sentence is not in itself a finding about the gene and the disease.
tumor (continued). "After using wild-type Tregs and Nrp1L/L Tregs to induce TAMs in the TME, researchers found that Nrp1- induced phenotype identification in M2-like mice with a reduced immune response to the tumor-like TME." (PMID 40216744, 2025). "Recent studies on NRP1 show restricted CD8+ T cell reinvigoration in response to ICIs by providing a barrier in CD8+ T cells mediated tumor immunosurveillance." (PMID 40277760, 2025). "Evidence indicates that NRP1 contributes to tumor growth by modulating autophagy and alternatively, interacts with autophagy to promote tumor progression and the acquisition of chemoresistance." (PMID 40314246, 2025). "NRP1 suppresses anti-tumor immune responses by enhancing regulatory T cell infiltration and promoting immune escape." (PMID 40257955, 2025). "NRP1, expressed by neuronal, epithelial, inflammatory, and tumor cells, binds VEGF to form a ternary complex with VEGF on endothelial cells, stimulating downstream signaling, which induces proliferation and migration." (PMID 40277760, 2025). "Mike B Barnkob and his team reported that NRP1 KO mice and genetic models of Sema3A in cancer cells, T cell expression of NRP1, and tumor cell expression of Sema3A can control CD8+ T cell infiltration." (PMID 40277760, 2025). "Biochemical and structural analyses subsequently mapped CTX mechanisms of action, revealing direct interactions with tumor-associated membrane proteins, such as MMP-2 and NRP1." (PMID 41155199, 2025). "In summary, VEGF and NRP1 are integral to cancer pathology, mainly through their roles in promoting angiogenesis, tumor growth, and metastasis." (PMID 40277760, 2025). "NRP1 (Neuropilin-1) functions as an “immune memory checkpoint” limiting the development of long-lived tumor-specific T cells, which are essential for maintaining durable antitumor immunity." (PMID 40299539, 2025). "EZH2 directly regulates neuropilin-1 (NRP1) expression, driving tumor growth and resistance to irinotecan." (PMID 40314246, 2025). "Such mass spectrometry-based proteomics-driven discoveries have expanded the CTX interactome beyond MMP-2, ClC-3, and annexin A2, highlighting neuropilin-1 (NRP1) as another critical binding partner for tumor selectivity." (PMID 41155199, 2025). "It has been shown that inhibition of NRP-1 can deplete intratumoral regulatory T cells (Tregs) that mediate resistance to anti-PD-1 immunotherapy, thereby restoring T cell-mediated anti-tumor responses." (PMID 40430075, 2025). "NRP1 knockdown promoted apoptosis and suppressed proliferation, angiogenesis, migration, and invasion, indicating NRP1 as a tumor promoter." (PMID 40277760, 2025). "We assessed NRP1 expression in tumor-associated microglia/macrophages (TAMs) and endothelial cells, as well as GFAP expression in astrocytes and tumor cells." (PMID 40805120, 2025). "However, most studies focused on the expression of NRP1 in the tumor cells themselves, where it is differentially expressed in the various molecular subgroups associated with poor prognosis, as it is involved in promoting metastasis, angiogenesis, and overall tumor progression." (PMID 40805120, 2025). "NRP-1 has a vital role in angiogenesis, and it is overexpressed in tumor cells, especially in GBM cell lines, such as T98G and A172." (PMID 40019229, 2025). "Flow cytometry and fluorescence imaging experiments confirmed that NGF effectively targets tumor cells expressing high levels of NRP1 and GLUT1, aligning with their respective expression profiles." (PMID 40048021, 2025). "Nrp-1 expression was reduced by Treg cells in Atg5ΔOX40 mice, which led us to investigate Treg cells in a tumor setting in these mice." (PMID 40977681, 2025). "This formation leads to an increase in the p38 MAPK pathway, as Rho A and MAPK are interdependent, so when NRP1/GIPC1 are suppressed, there is a suppression observed in Rho A and MAPK, leading to loss of the ECS phenotype and reduction in the tumor growth." (PMID 40277760, 2025).
tumor (continued). "Developing targeted drugs against NRP1 is critical for inhibiting communication between cancer cells and their microenvironment, thereby restraining tumor growth and spread." (PMID 40048021, 2025). "In contrast, low-risk tumors exhibited higher expression of HHLA2, NRP1 and TNFSF15, which are associated with a more balanced immune response and anti-tumor activity." (PMID 40243888, 2025). "By encouraging their recruitment to the tumor bed and maintaining their functional stability amidst continuing inflammation, NRP1 promotes the activity of intratumoral Treg cells." (PMID 40277760, 2025). "This review explores the diverse functions of NRP1 in cancer, encompassing its influence on tumor cell proliferation, migration, invasion, and metastasis." (PMID 40277760, 2025). "Further complicating matters, while VEGFR1 and NRP1 are highly expressed on endothelial cells, they are both also expressed with varying cell surface densities on macrophages and tumor cells." (PMID 41306516, 2025). "EG00229 has anti-tumoral activity in different tumours, inhibiting NRP1-dependent endothelial and tumour cell migration downstream of VEGFA." (PMID 38323651, 2024). "We previously clarified that TAGLN2 also plays an important role in promoting tumor angiogenesis by activating NRP1/VEGFR2 and downstream MAPK signaling pathways." (PMID 39168971, 2024). "It was shown that antibodies blocking VEGF binding to neuropilin-1 enhanced the anti-tumor effect of anti-VEGF antibodies." (PMID 38375479, 2024). "Studies have shown that NRP-1 is frequently overexpressed in various human tumor types, including breast cancer, melanoma, glioblastoma, leukemia, and others." (PMID 39518096, 2024). "The iRGD peptide demonstrates improved tumor targeting and penetration abilities via dual receptor binding (integrins and NRP‐1), while the cyclic structure of CRGDK offers enhanced stability against proteolytic degradation." (PMID 38349028, 2024). "Crosstalk between the VEGF and Notch pathways has emerged in tumor angiogenesis: notch signaling alters the expression of receptors (NRP1/2 and VEGFR1/2/3), promoting VEGF signaling." (PMID 38817877, 2024). "Overexpressed in several cancers, NRP-1 enhances tumor growth by promoting angiogenesis and cell migration, often in conjunction with vascular endothelial growth factor (VEGF)." (PMID 39598465, 2024). "EG00229, an inhibitor of neuropilin-1 has also been shown to possess significant tumor-suppressive effects in gliomas and squamous cell carcinomas." (PMID 38375479, 2024). "This exposed motif binds to neuropilin-1 (NRP-1), a receptor upregulated in aggressive tumors, promoting the deeper penetration of iRGD and its cargo into the extravascular tumor parenchyma." (PMID 39339166, 2024). "In tumor blood vessels, two key molecules, neuropilin-1 (NRP-1) and neuropolin-2 (NRP-2), can regulate the vascular permeability of tumor tissue and enhance permeability through the interaction between the C-end rule (CendR) motif and neuromycin." (PMID 39518096, 2024). "As Tregs transition from lymphoid tissues to the tumor, a progression from Nrp-1 + 4-1BB- Tregs to Nrp-1- 4-1BB+ Tregs was reported." (PMID 38571964, 2024). "Their findings showed that blocking NRP1 reduced angiogenesis and cell migration, ultimately inhibiting tumor growth." (PMID 39685591, 2024). "By binding to NRP-1, iRGD induces transient permeability in tumor vessels and surrounding ECM, effectively lowering resistance caused by high TIP." (PMID 39594723, 2024). "In previous studies, the high expression of NRP1, together with the occurrence of VM, has been linked to unfavorable outcomes in patients with TNBC as it promotes tumor proliferation and metastasis." (PMID 38728245, 2024). "Here the authors investigate how these interactions affect CD8+ T cells in tumour immunity, showing that NRP-1, Plexin-A1 and Plexin-A4 are upregulated on T cells allowing tumour derived SEMA3A to inhibit CD8+ T cell migration and function." (PMID 38609390, 2024).
tumor (continued). "Zhu and colleagues reported Nrp1’s critical role in restricting CCA tumor cell proliferation and migration, and further inhibiting the tumor progression and lung metastasis in vitro and vivo experiments." (PMID 39156971, 2024). "Upon binding, iRGD undergoes proteolytic cleavage, exposing the CendR motif (C-end rule), which activates neuropilin-1 (NRP-1) receptors on tumor cells." (PMID 39411070, 2024). "Others have indeed shown that anti-NRP1 antibodies can affect tumor growth in mouse models, likely by both inhibiting Treg cells and, as we show here, by decreasing the effects of SEMA3A on CD8+ effector T cells." (PMID 38609390, 2024). "New subpopulations of anti-tumor Tregs, such as Neuropilin-1−(Nrp1)−Tregs and TIGIT−Tregs, are continuously being discovered due to the use of single-cell sequencing technologies." (PMID 38509593, 2024). "In vitro, experiments support the inhibiting role of iRGD in tumor migration and enhancement of chemorepulsion based on a CendR/NRP-1 dependent mechanism." (PMID 39594723, 2024). "Significantly more CD8+ T cells in both tumor and tumor-adjacent tissue expressed NRP1, suggesting that these cells would be sensitive to SEMA3A." (PMID 38609390, 2024). "The iRGD-induced tumour-to-blood transport of AFP was found to depend on neuropilin-1 and on the concentration gradient between the tumour and the blood, and was primarily seen in animals with small tumours and basally normal blood AFP levels." (PMID 38889481, 2024). "Most likely, the remarkable control of tumor growth seen by us and others is due to synergistic effects between NRP1 knockout on both regulatory T cells and CD8+ T cells." (PMID 38609390, 2024). "This preferential interaction and increased affinity facilitate the transition of the CRGDK fragment from integrins to neuropilin-1, enhancing tumor infiltration." (PMID 39518096, 2024). "Nrp1− Tregs not only lose their immunosuppressive role, but also become active participants in the anti-tumor immune response." (PMID 38509593, 2024). "NRP1 is commonly expressed in endothelial cells and some tumor cells, and plays an important function in angiogenesis and tumorigenesis." (PMID 39014364, 2024). "NRP1 is highly expressed in many tumor tissues and participates in cell angiogenesis, growth and metastasis." (PMID 39014364, 2024). "Tregs, known for their highly suppressive and hyperproliferative features in the TME, express heightened levels of CD25, CTLA4, GITR, OX40, ICOS, and neuropilin-1 and accumulate significantly during tumor development." (PMID 38787791, 2024). "By targeting the neuropilin-1 transport system, the peptide component of the siRNA nanoparticle enabled extensive distribution of the therapeutic siRNA throughout the tumor." (PMID 39683699, 2024). "In conclusion, this work identified the first PARP1/NRP1 dual-targeted inhibitor and provided an effective strategy for constructing dual-targeted drugs for efficient tumor therapy." (PMID 39679370, 2024). "In this, we detected high mRNA level of NRP1 in BCa tumor tissues and confirmed that NRP1 level was positively correlated with IGF2BP2 mRNA level." (PMID 39014364, 2024). "Its interaction with these factors makes NRP-1 a valuable target for imaging and therapies aimed at disrupting tumor vasculature and limiting cancer spread." (PMID 39598465, 2024). "Its binding to NRP-1 facilitates extravasation, and it explicitly targets tumor cells overexpressing ανβ3/ανβ5 integrins while exhibiting low toxicity to normal cells." (PMID 39594723, 2024). "Upon cleavage into CRGDK/R, the exposed C-endR motif (R/KXXR/K) allows the fragmented peptide to enable the tumor microenvironment (TME) vasculature permeability through neuropilin-1 (NRP-1) interactions." (PMID 40603538, 2024). "Neuropilin-1 expression in tumor endothelial cells, through its interaction with VEGF stimulates angiogenesis by enhancing VEGF signaling." (PMID 38375479, 2024).
tumor (continued). "The in vitro study of PTX-SM-TAR NPs exhibited higher binding affinity to NRP1 (Neuropilin 1, tumor angiogenesis receptor), great transvascular transport, and tumor penetration ability." (PMID 38893132, 2024). "The effect was primarily seen in mice with small tumours and normal basal blood AFP levels, was attenuated by an anti-neuropilin-1 antibody, and depended on the concentration gradient between tumour and blood." (PMID 38889481, 2024). "Targeting NRP-1, which is overexpressed in tumor endothelial cells and tumor cells, offers the possibility of transporting the Dox-loaded particle efficiently and deep into the tumor." (PMID 38531786, 2024). "NRP1 expression levels were significantly upregulated in GC tissues and had positive correlation with the advanced tumor stage and worse clinical outcomes in GC patients." (PMID 39074262, 2024). "The majority of tumor-infiltrating Tregs express Nrp1, which interacts with its ligand, semaphorin 4A (Sema4A)." (PMID 39000453, 2024). "The majority tumor-infiltrating Tregs express Nrp1, which enhances their immunosuppressive role by interacting with Semaphorin 4A (Sema4A)." (PMID 38509593, 2024). "By binding to VEGF, NRP1 promotes angiogenesis, which is crucial for tumor growth and metastasis across multiple cancer types." (PMID 39334861, 2024). "In contrast to the EPR-dependent polyplexes, these NRP-1-dependent polyplexes are less dependent on the size for their tumor uptake." (PMID 39683699, 2024). "Neuropilin 1 (NRP1) is a transmembrane protein that mediates cytokine signaling and is associated with increased VEGF expression, promoting angiogenesis and tumor growth." (PMID 39334861, 2024). "Neuropilin-1 (NRP1) is a glycoprotein that is present in all nuclear tissues and performs multiple biological functions as such angiogenesis, tumor development, and immune system function." (PMID 39187525, 2024). "Previous work has shown that the association of PS with NRP-1-targeting molecules promotes the vascular effect of PDT, ultimately resulting in reduced tumor blood flow and delayed tumor growth." (PMID 39201395, 2024). "In summary, a series of HK siRNA polyplexes with an NRP-1 tumor-targeting component reduced luciferase levels in two tumor models." (PMID 39683699, 2024). "VEGFA can further induce the expression of neuropilin 1 (NRP1) in Tregs, which promotes the aggregation of Tregs around tumor blood vessels, thereby promoting Treg aggregation around tumor blood vessels." (PMID 38500876, 2024). "NRP-1 plays an essential role in iRGD-induced extravasation in tumours, and CendR peptide-induced vascular permeability." (PMID 38889481, 2024). "By exploiting both integrin-mediated targeting and NRP-1-facilitated penetration, iRGD offers a novel strategy for efficient tumor theragnostic." (PMID 39339166, 2024). "We show that initial NRP1 expression is controlled by the level of TCR-engagement, that the protein remains expressed on tumor-specific CD8+ T cells in vivo and that NRP1 is found on a subset of tumor-specific CD8+ T cells in human ccRCC patients." (PMID 38609390, 2024). "MUC1 induces angiogenesis in tumor microenvironments by increasing the expression of neuropilin-1(NRP1, a co-receptor of VEGF) and its ligand VEGF51." (PMID 38164273, 2024). "These NRP-1-positive monocytes, when injected into tumors, promoted the normalization of tumor vasculature." (PMID 39857591, 2024). "Taken together, our data underscores the functional significance of SEMA3A within the TME as a potent inhibitor of CD8+ T cell migration, and thereby anti-tumor immunity, via interaction with NRP1." (PMID 38609390, 2024). "Taken together these data show that NRP1+ CD8+ TILs were found in ccRCC patients, were activated and were likely specific for tumor-associated antigens." (PMID 38609390, 2024). "PEI-elastase also facilitated gene entry into tumor cells via NRP1-mediated transcytosis and PEI-mediated endocytosis." (PMID 39068444, 2024).
tumor (continued). "We find that the effects of SEMA3A on CD8+ T cells are mainly mediated through the co-receptor NRP1, which is retained on recently activated and tumor-specific T cells within the TME." (PMID 38609390, 2024). "Using T-cell-specific NRP1 knockout (KO) mice and genetic models of SEMA3A in cancer cells, we show that T cell expression of NRP1 and tumor cell expression of SEMA3A controls CD8+ T cell infiltration." (PMID 38609390, 2024). "Neuropilin 1 is a transmembrane protein that plays a significant role in the pathogenesis of tumor development." (PMID 39334861, 2024). "NRP1 has been defined as a novel immune checkpoint, and its blockade can enhance T-cell-mediated anti-tumor effects and restore anti-tumor T-cell memory." (PMID 37190154, 2023). "TAR peptide can also target NRP-1 for cargo delivery and effectively penetrate the tumor barrier, which has been used for DNA delivery for the treatment of glioma." (PMID 36902076, 2023). "Through UALCAN database, a significantly increased NRP1 expression was identified in the primary tumor tissue of HCC samples compared to healthy normal tissue from the TCGA." (PMID 36376373, 2023). "(+) Selective uptake in neuropilin-1 rich organs.(+) Reduced tumor burden (paclitaxel cumulative dose injected 7 mg/kg).(+) In CT26 model, reduction of ascites volume." (PMID 37287910, 2023). "A previous study reported that NRP1 can act as a co-receptor of multiple tyrosine kinase receptors to promote tumor proliferation and migration." (PMID 36841806, 2023). "In PCa cells, NRP1 promoted malignant phenotypes, including cell viability and migration, tumor growth, and metastasis." (PMID 36841806, 2023). "Treg-specific Nrp-1 depletion resulted in less stability and function of intratumoral Tregs and a decrease in tumor volume." (PMID 38019895, 2023). "Blockade of NRP1 function induced by peptide N results in inhibition of vascular remodeling and tumor growth in mice with HCC." (PMID 37894289, 2023). "TAR showed a strong binding ability to NRP-1 with a KD value of 3.397 × 10−8 M. TAR peptide labeled with fluorescein Cy5.5-MAL was used to analyze the tumor-targeting delivery ability of a TAR peptide in vivo." (PMID 36902076, 2023). "A separate study gave an alternative approach using LAMP2b to demonstrate hepatopeptide tLyp-1 (CGNKRTR) as a binding to neurofibrillary protein 1/2 (NRP1/2) highly expressed on tumor cell membranes specific ligand." (PMID 37670933, 2023). "In the hypoxic tumor microenvironment, elevated NRP1 expression was mediated by transcriptional regulation of HIF1α." (PMID 36841806, 2023). "CD8+ T cell-specific Nrp-1 knockout mice with a resection of the primary tumor were protected from secondary tumor challenge." (PMID 38019895, 2023). "His strategy was to chemically conjugate the hydrophilic peptide moiety iRGD (a tumor-penetrating peptide that can bind to neuropilin-1 and stimulate tumor tissue penetration) to the hydrophobic anticancer cargo CPT." (PMID 36587630, 2023). "For example, SERPINA1 showed close connections to CD8A in CD8+ T cells, CD68 in tumor-associated macrophages, IRF6 in M1 macrophages, NRP1 in DCs, STAT3 and IL17A in Th17 in most digestive cancers." (PMID 37511325, 2023). "Neuropilin-1 (Nrp-1) expression on CD8+ T cells has been identified in tumor-infiltrating lymphocytes and in persistent murine gamma-herpes virus infections, where it interferes with the development of long-lived memory T cell responses." (PMID 38019895, 2023). "tLyp-1, a tumor homing and penetrating peptide, was able to mediate tissue penetration through the NRP-1-dependent internalization pathway." (PMID 36762192, 2023). "Although NRP1 expression was firstly identified in the central nervous system, this receptor is expressed in different tissues, being overexpressed in several tumor types, including HCC." (PMID 36376373, 2023).